KLRG1 (killer cell lectin like receptor G1)
Diseases named in the same sentence as KLRG1 in open-access papers (continued):
Sharing a sentence is not in itself a finding about the gene and the disease.
liver fibrosis (5 papers, 2019 to 2025). "This antifibrotic function of KLRG1+ NK cells provides a new therapeutic approach for treating liver fibrosis in patients with CHB." (PMID 38898461, 2024). "The frequency of killer cell lectin-like receptor subfamily G member 1 (KLRG1)-expressing NK cells in the liver and blood of patients with CHB has been found to be negatively associated with liver fibrosis." (PMID 37239062, 2023). "In chronic HBV patients, elevated frequency of killer cell lectin-like receptor subfamily G member 1+ (KLRG1) NK cells are detected and are implicated to causes reduction in hepatic fibrosis." (PMID 34071188, 2021). "In CHB infection, KLRG1+ NK cells, the number of which is increased in PB and liver samples, can inhibit liver fibrosis by enhancing the apoptosis of activated hepatic stellate cells through the upregulation of expression of tumor necrosis factor-related apoptosis-inducing ligands." (PMID 38898461, 2024). "Wijaya demonstrated that KLRG1+ NK cells relied on the bone-bridging proteins TRAIL and CD44 to promote HSC apoptosis and mitigate hepatic fibrosis." (PMID 40244063, 2025). "Thus, KLRG1 expression identifies a beneficial subpopulation of NK cells that is enriched in patients with no liver fibrosis or mild liver fibrosis." (PMID 31614928, 2019).
lung carcinoma (5 papers, 2019 to 2024). "Our results also indicated that knockdown of KLRG1 promoted the proliferation of A549 lung cancer cells." (PMID 34187403, 2021). "Moreover, KLRG1 inhibition promotes the proliferation rate of A549 and H1299 lung cancer cells." (PMID 36428727, 2022). "It has also previously been found that in patients with lung cancer, circulating CD28−CD57+KLRG1+CD8+ T cells were associated with a lack of benefit from ICIs." (PMID 38404585, 2024).
non-small cell lung carcinoma (5 papers, 2022 to 2026). A group of at least three distinct histological types of lung cancer, including non-small cell squamous cell carcinoma, adenocarcinoma, and large cell carcinoma. "KLRG1, identified as a co-inhibitory receptor for natural killer (NK) cells and antigen-experienced T cells, has been implicated in immune regulation in patients with non-small cell lung cancer." (PMID 40654678, 2025). "In patients with advanced non-small cell lung cancer (NSCLC), a high number of peripheral blood circulating CD28− CD57+ KLRG-1+ CD8+ T cells is associated with a poor clinical response to PD-1 inhibitors." (PMID 35328795, 2022). "KLRG1+ Tregs have been identified in the tumor microenvironment of murine models and human samples of non-small cell lung cancer." (PMID 35634302, 2022).
type 1 diabetes (5 papers, 2017 to 2025). "Teplizumab-induced partial exhaustion of CD8+ T memory cells (KLRG1+TIGIT+) has been associated with a positive clinical response to teplizumab in stage 2 type 1 diabetes." (PMID 39560746, 2025). "Similarly, in a TCR transgenic NOD mouse model, KLRG1+ Tregs were unable to suppress the development of type 1 diabetes." (PMID 35634302, 2022). "In the nonobese diabetic mouse model of type 1 diabetes (T1D), KLRG1 is expressed on Foxp3+ Treg cells in the pancreatic islets and plays a role in inhibiting pancreatic autoimmunity, resulting in a decrease in the proliferative and inhibitory functions of Foxp3+ Treg cells." (PMID 38898461, 2024). "Building on our past findings of increased TIGIT+KLRG1+ TEX with teplizumab therapy in type 1 diabetes (T1D), in the absence of treatment we found that the frequency of TIGIT+KLRG1+ TEX is stable within an individual but differs across individuals in both T1D and healthy control (HC) cohorts." (PMID 38650930, 2024).
Allergy (4 papers, 2021 to 2025). An allergy is an immune response or reaction to substances that are usually not harmful. "Nonetheless, KLRG1 appears to mediate protective functions by ILC2s against infections and allergies." (PMID 37696896, 2023). "Interestingly, circulating KLRG1+ ILC2s from individuals with allergic disease were unable to generate IL-10, but this ability was recovered after effective allergen immunotherapy." (PMID 36960063, 2023). "Another study suggested that KLRG1+ ILC2s may help block allergies via ILCreg-like functions." (PMID 37696896, 2023). "Indeed, mTOR inhibition attenuated OVA-mRNA-LNP–induced CD8+ T cells in the lung and the CD38+KLRG1– CD8+ T cell subset, including perforin production, while preserving the anti-allergy effect of the vaccination." (PMID 40985871, 2025).
atopic dermatitis (4 papers, 2017 to 2021). "Higher frequencies of activated KLRG1 expressing ILC2 were detected in skin lesions of atopic dermatitis patients." (PMID 29587679, 2018). "E-cadherin, the ligand for killer cell lectin-like receptor subfamily G member 1 (KLRG1) expressed on ILC2s, has also been shown to downregulate ILC2 cytokine secretion and activation, though it was found in the context of atopic dermatitis." (PMID 34489979, 2021). "Patients with atopic dermatitis show increased expression of Klrg1 and the interaction of activated ILC2s with E-cadherin results in a down regulation of GATA-3, IL-5, IL-13, amphiregulin and reduced ILC2 proliferation; suggesting a negative regulatory role for Klrg1 in skin ILC2s." (PMID 34759931, 2021).
colon cancer (4 papers, 2016 to 2024). "Immunofluorescence cell staining confirmed the higher level of KLRG1 expression on CD3+ T cells in colon cancer tissue compared with the expression in colon tissue from patients received colectomy after trauma." (PMID 27557510, 2016). "We also found KLRG1 expression significantly increased in both CD4+ and CD8+ T cells in colon cancer, colitis and ovarian cancer." (PMID 27557510, 2016).
colorectal cancer (4 papers, 2018 to 2024). A primary or metastatic malignant neoplasm that affects the colon or rectum. "A multiplexed single-cell analysis study reveals KLRG1+ cytotoxic T cells were enriched in colorectal cancer patients with good outcomes." (PMID 37231145, 2023). "KLRG1 expressing NK cells protect against pulmonary metastatic disease and colorectal carcinoma." (PMID 29587679, 2018). "Furthermore, KLRG1+ cytotoxic T-cells are enriched in CRC patients with a good prognosis, and CD27lowKLRG1+ NK cells protect T-box expressed in T-cells (T-bet)-deficient mice from pulmonary metastatic colorectal carcinoma." (PMID 38898461, 2024). "KLRG-1+ CD8 T cells displayed a lower frequency in tumors compared with peripheral blood from patients with breast, cervical, esophageal, gastric, and colorectal cancers but not with kidney, lung, and liver cancers." (PMID 31709176, 2019).
latent infection (4 papers, 2015 to 2022). "Quantifying the cluster membership demonstrated a trend that those cells with higher expansion levels were located in cluster 1 for acute, 5 for chronic, 2 for latent infection, which characteristically expressed Zeb2, Tox, and Klrg1, respectively." (PMID 35185882, 2022). "More recently, it was reported that inflationary KLRG1+CD62L− cells in latent infection differ from KLRG1+CD62L− SLEC of the acute response, in that they have an extended life span due to IL-15-mediated expression of the anti-apoptotic protein Bcl-2, which makes them ‘memory cell-like’." (PMID 32707744, 2020).
Listeria infection (4 papers, 2012 to 2021). "Recently, Klrg1 lineage reporter mice have been developed to track the memory offspring of KLRG1+ cells after Listeria infection." (PMID 30131803, 2018). "Additionally, a recent study demonstrated how KLRG1+ IL‐7Rα+ effector cells can downregulate KLRG1 and differentiate into all memory subsets in response to secondary Listeria monocytogenes infection." (PMID 33037653, 2020). "To investigate the role of type I IFN in the differentiation into effector cells, we analyzed KLRG1 and CD127 expression on P14.WT, P14.IL-12RKO, P14.IFNARKO and P14.DOKO T cells in the spleen day 5 after Listeria infection." (PMID 22815848, 2012). "During both, VSV and Listeria infection, T cells lacking type I IFN and IL-12 signals down-regulated T-bet and up-regulated Eomes, thereby showing a memory CTL phenotype, with high CD127 and low KLRG1 expression." (PMID 22815848, 2012).
lung adenocarcinoma (4 papers, 2021 to 2024). A carcinoma that arises from the lung and is characterized by the presence of malignant glandular epithelial cells. "In the current study, we screened for genes associated with the prognosis of patients with lung adenocarcinoma and positively correlated with antigen-presenting cell infiltration and identified KLRG1 and CBFA2T3 as potential tumor antigens for mRNA vaccines in lung adenocarcinoma (LUAD)." (PMID 35265614, 2022). "On the contrary, there has also been reported that high KLRG1 expression is associated with low proliferation of lung adenocarcinoma cells, however, KLRG1 expression is often low in lung adenocarcinoma cells, and associated with adverse effects of immunotherapy." (PMID 35265614, 2022). "The low expression levels of down-regulated DEGs PLA2G3, PCP4L1, NINJ2, MIR186, and KLRG1 were also statistically correlated with a shorter OS in lung adenocarcinoma." (PMID 38183079, 2024). "Collectively, KLRG1 may be a powerful biomarker to support the diagnosis and predict the clinical benefit of immunotherapy in lung adenocarcinoma." (PMID 34187403, 2021). "This work intended to investigate the predictive ability of KLRG1 on the efficacy of immune-checkpoint inhibitor in the treatment of lung adenocarcinoma (LUAD), as well as contribute to the possible molecular mechanisms of KLRG1 on LUAD development." (PMID 34187403, 2021). "Altogether, the results presented here indicate that KLRG1, BTK, CCR2 and SCML4 play important roles in the development of lung adenocarcinoma, and their expression can be effective biomarkers to predict LUAD patients’ survival." (PMID 34187403, 2021). "In this study, through the analysis of the database and clinical samples, we found four markers (KLRG1, BTK, CCR2 and SCML4) which may play important roles in the development of lung adenocarcinoma." (PMID 34187403, 2021). "Of note, KLRG1 expression has been found to positively correlate with the efficacy of ICIs, demonstrating that, besides its negative role, KLRG1 may behave as a predictive biomarker of immunotherapy clinical benefit in lung adenocarcinoma." (PMID 36428727, 2022).
malaria (4 papers, 2013 to 2025). Malaria is a serious and sometimes fatal disease caused by a parasite that commonly infects a certain type of mosquito which feeds on humans. "We found that PD-1+, 4-1BB+, LAG-3+, KLRG1–, PLZF–, CTLA4+, and Siglec-7– NK cells were increased in individuals with malaria experience." (PMID 40337867, 2025). "Moreover, similar time course of expressions are detected, both by qRT-PCR and microarrays, for Klrg1 and Klrd1 as well as Klrb1f and Clec2i in both vaccinated and non-vaccinated mice in response to malaria and vaccination." (PMID 33202767, 2020).
asthma (3 papers, 2021 to 2025). "We report a higher frequency of CD62L+ ILC2s and a lower frequency of CD4+ KLRG1+ cells among TCM cells specifically in T2 asthma." (PMID 40965120, 2025). "The frequency of CD62L+ ILC2s was higher and CD4+ KLRG1+ central memory T cells was lower specifically in T2 asthma." (PMID 40965120, 2025). "In contrast, in CD4 cluster 9, we observed a lower frequency of CD4+ KLRG1+ cells among TCM cells in T2 asthma compared to non‐T2 asthma." (PMID 40965120, 2025). "However, the frequency of CD62L+ ILC2s was higher, and CD4+ KLRG1+ cells among TCM cells was lower only in T2 subjects with asthma." (PMID 40965120, 2025). "Notably, recent studies have also pointed toward the presence of KLRG1 as one of the main drivers of phenotypic differences in ILC2 that contribute to sex disparities in asthma where prevalence is greater in females compared to males, post-puberty." (PMID 37947634, 2023). "Importantly, only KLRG1 was associated with the sex disparities, and whether the KLRG1+ILC2 cells produce IL-10 and the association of IL-10+KLRG1+ILC2 and sex differences in asthma has not yet been investigated." (PMID 37947634, 2023).
Crohn disease (3 papers, 2020 to 2022). A gastrointestinal disorder characterized by chronic inflammation involving all layers of the intestinal wall, noncaseating granulomas affecting the intestinal wall and regional lymph nodes, and transmural fibrosis. "KLRG1+ CD8+ Trm cells are mostly found in the periphery and have a higher cytotoxic potential evidenced by the intracellular levels of granzyme B. In accordance, KLRG1+ CD8+ Trm cells were increased in inflamed tissue of Crohn’s disease patients compared to non-inflamed and controls." (PMID 34707610, 2021).
diabetes (3 papers, 2024 to 2025). "It was found that parental clinical manifestation of diabetes is significantly associated with shorter telomeres, TERT gene polymorphism and up-regulation of the immune senescence markers, especially the KLRG1 in newborns." (PMID 41168774, 2025). "The Newborns of parents with clinical manifestations of diabetes exhibited upregulation of KLRG1 markers and a correlation with shorter telomere length." (PMID 41168774, 2025). "In CD8 Tem cells, KLRG1 expression was elevated in individuals with T2D compared to non-diabetes." (PMID 39072276, 2024). "Mothers with diabetes and their newborns exhibited elevated levels of immune senescence markers (CD57+KLRG1+)(M: 6.63 ± 3.57, N: 3.5 ± 5.49), p = 0.02)." (PMID 41168774, 2025).
Ebola (3 papers, 2020 to 2023). "Importantly, a recent study found that the expansion of CD57+KLRG1+ T cells in CMV+ young adults is associated with a reduced Ebola vaccine response, suggesting that CMV infection could also have negative impacts on vaccination efficacy." (PMID 35822004, 2021).
glioblastoma (3 papers, 2023 to 2024). The most malignant astrocytic tumor (WHO grade IV). "Furthermore, Th17 (Tc-II 15) were higher and Th9 (Tc-II 7), CD4+ naïve Tc (Tc-I 8), and KLRG1+CD4−CD8− Tc (DN Tc) (Tc-I 30) were lower in glioblastoma in comparison to controls." (PMID 39497174, 2024). "In contrast, glioblastoma patients were mainly characterized by lower fractions of several T memory subsets, except for KLRG1+ CD4+ TTE, which were more abundant in the PB of glioblastoma patients in comparison to controls." (PMID 39497174, 2024). "Comparing glioblastoma and RRMS patients, we detected a decrease in KLRG1+CD4−CD8− Tc (Tc-I 30) in glioblastoma patients, also visible when comparing glioblastoma patients and controls." (PMID 39497174, 2024). "Tregs (Tc-II 11) were lower in RRMS and KLRG1+ (activated) CD8+ TTM (Tc-I-26 & Tc-I 33) and (activated) CD8+ TTE (Tc-I 19 & Tc-I 27) higher in RRMS in relation to glioblastoma patients similar to the comparison between RRMS patients and controls." (PMID 39497174, 2024). "Comparable to glioblastoma patients, RRMS patients had higher fractions of KLRG1+CD4+ TTE (Tc-I 25) and reduced percentages of KLRG1+CD4+ TTM (Tc-I 6), KLRG1+CD4+ TCM (Tc-I 3), CD4+ TEM (Tc-I 11), and Th9 (Tc-II 7) compared to controls." (PMID 39497174, 2024). "In addition, glioblastoma and RRMS patients shared higher fractions of KLRG1+ CD4+ TTE, whereas CD8+ effector and memory Tc were only elevated in RRMS patients compared to controls." (PMID 39497174, 2024). "Furthermore, in-depth phenotyping of PB immune cells also revealed changes in the effector and memory Tc compartment with similarities in KLRG1+ CD4+ TTE between RRMS and glioblastoma patients and differences in CD8+ effector and memory Tc and activated CD4+ TSCM." (PMID 39497174, 2024).
glioma (3 papers, 2020 to 2026). A benign or malignant brain and spinal cord tumor that arises from glial cells (astrocytes, oligodendrocytes, ependymal cells). "An oncolytic HSV expressing E-cadherin, a ligand for the inhibitory NK receptor KLRG1, resulted in a better outcome in a glioma mouse model, by inhibiting NK cells and permitting viral spread." (PMID 33154756, 2020). "Tumor and peripheral blood samples from 32 glioma patients (WHO 2021 classification, grades II-IV) were analyzed by flow cytometry to assess ILC subsets and immunecheckpoint molecules (PD-1, CTLA-4, KLRG1)." (PMID 41917320, 2026).
lymphopenia (3 papers, 2024 to 2025). Reduction in the number of lymphocytes. "KLRG1 is expressed on a subset of mature NK cells and can be upregulated in response to proliferation in a host with lymphopenia." (PMID 38895234, 2024). "The expression of KLRG-1 and GZMK was not increased with lymphopenia." (PMID 40612959, 2025).
ovarian carcinoma (3 papers, 2016 to 2023). A malignant neoplasm originating from the surface ovarian epithelium. "A further implication from our study points to LAG-3 and KLRG1 checkpoint receptors that may contribute to the immunotherapy resistance in patients with ovarian cancer." (PMID 38032111, 2023). "In contrast, T cells isolated from ovarian cancer and colitis expressed high level of KLRG1." (PMID 27557510, 2016). "We could speculate that the low activity of T cells in immunologically non-responding patients with ovarian cancer may be more affected by their potentially upregulated LAG-3 and KLRG1 coinhibitory/checkpoint receptors than PD-1 receptors." (PMID 38032111, 2023).
co-infection (2 papers, 2021 to 2025). "Analysis of SFV-specific CD8+ T cells demonstrated SFV-only infection to have higher frequency of CD25+CD38+ double positive phenotype, whereas IAV→SFV co-infection had higher KLRG1+CD38+ expression." (PMID 39817772, 2025). "Co-infection was also exemplified by a consistently increased effector-memory phenotype (i.e., CD44+ KLRG1+) of the GP33-specific CD8+ T cells in blood." (PMID 33458613, 2021). "Cytosplore analysis based on the markers CD44, CD62L, and KLRG1 revealed that at the peak of the effector response, the phenotype of the GP33-specific CD8+ T cells in the blood upon LCMV Armstrong infection resembled the phenotype of the GP33-specific CD8+ T cells that develop during co-infection." (PMID 33458613, 2021).
colitis (2 papers, 2016 to 2022). Inflammation of the colon. "Several studies have indicated that KLRG1+ Tregs aggregate at sites of inflammation such as virally infected lungs, Peyer’s patches, and Lamina propria in the murine model of colitis or injured skeletal muscles." (PMID 35572605, 2022). "Finally, in a T-cell induced colitis model, it was revealed that Treg cells convert to KLRG1+ effector Tregs that express heightened αvβ8 integrin." (PMID 35572605, 2022).
HIV-1 infection (2 papers, 2017 to 2022). The type species of lentivirus and the etiologic agent of acquired immunodeficiency syndrome (AIDS). "Similarly, we found rapid increases of KLRG1, LAG-3, PD-1, and TIGIT expression in blood and tissue NK cells within 2 weeks after HIV-1 infection." (PMID 36282589, 2022).
immune deficiency (2 papers, 2015 to 2017). "Naive wild-type (WT), Fcgr3−/− (FcγRIII−/−) or SCID (severe combined immune deficiency) mice were treated with a single dose of anti-CD27, and the expression of the activation marker, KLRG1, was monitored on peripheral blood NK cells." (PMID 29198913, 2017).
inclusion body myositis (2 papers, 2024 to 2025). A slowly progressive degenerative inflammatory disorder of skeletal muscles characterized by late onset weakness of specific muscles and distinctive histopathological features. "Inclusion body myositis (IBM) is an idiopathic inflammatory myopathy characterized by muscle-infiltrating KLRG1+ and TBX21+ cytotoxic T cells and type 1 inflammation." (PMID 40502583, 2025). "Finally, recent clinical studies of KLRG1 inhibitors have focused only on inclusion body myositis (IBM) and T-cell large granular lymphocytic leukemia diseases, and the feasibility of using KLRG1 as a potential therapeutic target for other diseases still needs to be studied." (PMID 38898461, 2024).